SAG (S-antigen visual arrestin)
Diseases named in the same sentence as SAG in open-access papers (continued):
Sharing a sentence is not in itself a finding about the gene and the disease.
pharyngitis (1 paper, 2012). Inflammation of the throat most often caused by viral and bacterial infections. "On the other hand, we identified an association of pharyngitis isolates with emm types 4 and 75, and with the SAg genes speC, ssa, and speL/M." (PMID 23181337, 2012). "Other individual emm alleles and SAg genes were also associated with a higher propensity to cause invasive infections or pharyngitis indicating the importance of these characteristics in determining an isolate’s invasive capacity." (PMID 23181337, 2012).
schizophrenia (1 paper, 2024). A major psychotic disorder characterized by abnormalities in the perception or expression of reality. "Besides, PDE4A was related to heat shock protein B6 (HSPB6), aldehyde dehydrogenase 7A1 (ALDH7A1), A-kinase anchoring protein 1 (AKAP1), adrenoceptor beta 2 (ADRB2), SAG (an arrestin family member which desensitizes GPCR) and DISC1 (disrupted in Schizophrenia 1)." (PMID 38514754, 2024).
toxoplasmosis (1 paper, 2021). A parasitic disease contracted by the ingestion or fetal transmission of toxoplasma gondii. "However, the sensitivity limit of SAG-4 and MAG-1 was about 1 parasite/ml and thus B1 had a higher sensitivity than SAG-4 and MAG-1 genes for toxoplasmosis diagnosis." (PMID 34814840, 2021).
tuberculosis (1 paper, 2015). A chronic, recurrent infection caused by the bacterium Mycobacterium tuberculosis. "This information is rather important in context to the evidence that showed no direct involvement of CD1d in tuberculosis antigen presentation and to other reports suggesting non-conventional sAg presenting sites." (PMID 25649790, 2015).
infection (20 papers, 2008 to 2025). The state of being infected such as from the introduction of a foreign agent such as serum, vaccine, antigenic substance or organism. "Based on comparisons with the earlier MRSA isolate from the same patient and combined with experimental infection models, we found that the increased persistence of these MSSA strains was associated with the production of plasmid-encoded SAg toxins." (PMID 39878522, 2025). "For E. tenella we specifically studied genes with putative involvement in host cell invasion and infection such as SAG genes, rhoptry kinase (ROPK) genes, rhoptry neck protein (RON) genes, dense granule (GRA) genes and microneme (MIC) genes." (PMID 33536090, 2021). "During infection, the draining lymph node is the most likely site for SAg to interact with Vβ T cells as well as APCs." (PMID 31412561, 2019). "SAG was previously reported to maintain macrophage survival and to regulate the levels of inflammatory cytokines in response to infection by ubiquitinating the pro-apoptotic proteins Bax and SARM." (PMID 30574150, 2018). "Previous studies have demonstrated that SAG regulates other innate immune cell responses, such as DCs and macrophages during infection." (PMID 30574150, 2018). "Depletion of mGli2 from NIH3T3 cells abolished SAG-stimulated Kapβ2 up-regulation, which was rescued by lentiviral infection of exogenous mGli2, suggesting that Smo activation induces Kapβ2 expression through Gli." (PMID 28777795, 2017). "To explore the clinical significance of SAG-UPS in response to infection and disease progression, here we performed a retrospective study on the impact of SAG on human primary HCC tissues." (PMID 27551463, 2015). "SAG-ubiquitination of pro-apoptotic factors strategically supports macrophage survival, sustaining immune defense during early infection." (PMID 26492374, 2015). "Our previous study has suggested that SAG-UPS plays a role in the life/death of macrophages during infection-mediated inflammation and it induces a protumorigenic microenvironment." (PMID 27551463, 2015). "Using in vitro and ex vivo approaches, Chang and Ding2 have recently shown that survival advantage to the macrophages during early infection is conferred by the protective potency of SAG (sensitive to apoptosis gene)." (PMID 26492374, 2015). "To assess the requirement for SAg activity for the infection phenotype, we constructed a SpeA MHC-II binding mutant based on a structural model of SpeA in complex with HLA-DQ8." (PMID 24875883, 2014). "After Psm ES4326 infection, in wild type, SA+SAG content was approximately 10-fold higher than SA content." (PMID 19117519, 2008). "A critical SAg involvement in establishing infection of its natural niche has been discovered for S. pyogenes, and a role for SAgs in promoting survival of S. aureus during infection has been identified." (PMID 28880913, 2017). "Studies with primary bone marrow-derived macrophage cells have demonstrated that SAG has a key regulatory role in balancing the ratio of pro- and antiapoptotic factors in the infection challenged macrophages, as indicated by the production of both pro- and anti-tumorigenic cytokines." (PMID 26492374, 2015). "The higher invasive capacity of this clone cannot be attributed to its SAg repertoire, since these isolates do not harbor any of the SAg genes associated with invasive infection." (PMID 23181337, 2012). "Psm ES4326 infection induced less SA and SAG accumulation in sid2-2 than in wild type." (PMID 19117519, 2008). "SAg may play a role in driving tonsillar hyperplasia in some individuals by disabling or subverting the local tonsil T cell response, including innate lymphoid cells such as MAIT cells, to facilitate ongoing susceptibility to infection." (PMID 31252586, 2019).
infection (continued). "In xopB-overexpressing Arabidopsis plants, however, both the increase in the amount of SA/SAG as well as in PR gene expression was clearly lower in response to Pst DC3000 infection than in wild type plants indicating that XopB suppresses defence responses during infection with Pst DC3000." (PMID 27398933, 2016). "Thus, pre-existing anti-SAg antibodies may potentially inhibit infection by specific strains of S. pyogenes, yet S. pyogenes could theoretically circumvent this through up-regulation of additional SAgs for which neutralizing antibodies are absent." (PMID 24875883, 2014). "Currently, we demonstrated that TGFβ1 and SAG maintain BBB integrity and suppress BMECs immune reaction induced by meningitic E. coli, which indicated protective potential of HH signaling agonist onto CNS upon infection." (PMID 38360663, 2024). "SAG suppressed ERK1/2 phosphorylation, IL-6, MIP-2, and E-selectin upregulation upon infection." (PMID 38360663, 2024). "In contrast to CEVd infection, SAG accumulation was not induced by Pst in both transgenic lines according to the results obtained using fluorescence-based detection." (PMID 36443652, 2022). "In contrast, for hedgehog agonist SAG, both pre-treatment and co-treatment of SAG in mice, all exhibited the protective effects against RS218 challenge, which supported a promising potential of SAG in control of the infection, especially when applied simultaneously." (PMID 34281571, 2021). "Before infection, meaning 18 h after induction of xopB expression, XopB did not significantly influence the amounts of SA and SAG." (PMID 27398933, 2016).
tumor (18 papers, 2002 to 2026). "The immunotoxin naptumomab estafenatox was developed in an effort to activate and target the patient’s own T cells to their tumor, by fusing a superantigen (SAg) variant that activates T lymphocytes to the Fab moiety of a tumor-reactive monoclonal antibody." (PMID 24445502, 2014). "Thus, accumulation of PHLPP1 or DEPTOR upon SAG knockdown plays at least in part a causal role in suppression of tumor cell growth and reverse of tumor cell phenotypes." (PMID 27955654, 2016). "As expected, 4T1 tumor-bearing nude mice that received 4T1-primed CD3+ T cells produced high amounts of RANKL in response to sAg stimulation." (PMID 41364090, 2026). "Total CD19+ B cells isolated from the iliac bones of tumor-free mice and animals bearing either 67NR or 4T1 tumors were cultured in vitro and stimulated with tumor-derived sAg." (PMID 41364090, 2026). "Twenty-one days after transfer, total spleen and BM cells from each group were cultured in vitro and restimulated with 4T1 tumor–derived sAg." (PMID 41364090, 2026). "Transgenic expression of SAG in mouse skin impairs tumor formation at early stages by targeting c-Jun/AP1 for degradation, whereas it promoted tumor growth at later stages by targeting IκBα to activate NF-κB." (PMID 31926110, 2020). "Studies have shown that inactivation of SAG reduces the viability of tumor cells and infected murine macrophages in vitro." (PMID 30574150, 2018). "The Asp477Gly mutation in the 7TM binding-site of SMO, initially isolated from a patient whose tumor had become resistant to vismodegib, reduces binding and responsiveness to a subset of 7TM ligands, including SAG and vismodegib." (PMID 27705744, 2016). "Further work is warranted to explore potential contributions of SAG-UPS to the recruitment of immune cells to a tumor microenvironment in the background of chronic infection." (PMID 27551463, 2015). "This study aimed to investigate how vSAG7 activated T lymphocytes kill SAG expressing tumour cells and to obtain more insights into the mechanism of SAG specific tumour cell lysis and GvL activity." (PMID 11875749, 2002). "This kill is SAG-specific and occurs in several tumour cells that express this endogenous viral superantigen." (PMID 11875749, 2002). "To establish whether TPL could restrict tumor growth by preventing the Hh pathway, we applied SAG to further stimulate this pathway in EOC cells." (PMID 37851362, 2023). "Because SAG/E3 targets several tumor suppressors for degradation, it is regarded as an oncoprotein." (PMID 31926110, 2020). "Interestingly, the β1-subunit mRNA level in SAG-treated cells was similar to that of primary cultures of tumor cells from Smo/Smo mice." (PMID 26286140, 2015). "Likewise, the inability of scFv5T4 alone, or the inactive scFv5T4::SpeCY15A/D203A fusion to show any measurable impact demonstrates that T cell-dependent SAg activity was also required for tumor cell killing." (PMID 24736661, 2014). "rSElW is a highly prevalent SAg that binds to the TCR via C98 and C88, which may serve as novel therapeutic targets for S. aureus infections and its application in anti-tumor activity needs to be further evaluated in vivo." (PMID 40887860, 2025). "In YTHDF1 knockdown tumor cells, only RNF7 (RING Finger protein 7), also known as SAG (Sensitive to Apoptosis Gene), a crucial subunit of the RBX/ROC RING of E3 ubiquitin ligase essential for cancer cell growth, was significantly reduced compared to control cells." (PMID 40251202, 2025). "Its oncogenic or tumor suppressor activities are mainly mediated by ubiquitination of proteins with oncogenic or tumor suppressor functions such as PTEN, MDM2, CNrasGEF, N-Myc and C-Myc, Her3, SAG, AKT, and Ras." (PMID 36918822, 2023).
cancer (11 papers, 2012 to 2025). A tumor composed of atypical neoplastic, often pleomorphic cells that invade other tissues. "In fact, in the last few years, SAgs, SAg-like proteins and SAg derivatives have been extensively investigated as immune-modifiers in the treatment of cancer, either alone or in combination with classical antitumor drugs." (PMID 37377961, 2023). "The results showed that the level of SAG expression correlated positively with the level of COPB2 expression in several human cancer cell lines." (PMID 31926110, 2020). "In summary, our findings demonstrate for the first time the molecular mechanisms underlying how SAG-UPS regulates immune overactivation and protumorigenesis, linking immunology and cancer biology." (PMID 27551463, 2015). "Being a crucial member at the crossroad between inflammation and cancer, SAG appears to be an important modulator of proinflammatory/protumorigenic molecules (IL-1β, IL-6 and TNF)." (PMID 27551463, 2015). "They demonstrated that SAG is upregulated in the early stage carcinoma tissues and further showed that SAG-UPS perturbs the fine balance of the ratio of pro-apoptotic (SARM and Noxa) and antiapoptotic factors." (PMID 26492374, 2015). "Coincidently, we found that protumorigenic/proinflammatory cytokines, IL-1β, IL-6 and TNF, along with SAG, were significantly upregulated in the primary carcinoma tissues (P<0.01)." (PMID 27551463, 2015). "We next inquired if the SHH signaling pathway agonist, SAG, which acts by directly binding to downstream Smoothened, would promote cancer cell growth." (PMID 23762282, 2013). "Furthermore, PTX and Gαt remarkably abolished the phosphorylation of JNK in response to SAG in chemoresistant cancer cells K562/A02." (PMID 24393163, 2014). "Here, we explored the novel regulatory mechanisms of SAG-dependent UPS in HCC, a major form of deadly cancer worldwide." (PMID 27551463, 2015). "Upregulated SAG-UPS effectively manipulates the levels of high-molecular-weight ubiquitinated SARM and Noxa in carcinoma tissues compared with corresponding normal tissues." (PMID 27551463, 2015). "All the down-regulated genes, in this Panel 3 showed their significant up-regulation in most of many types of cancers (TGM2, CSNK1A1, CTNNA1, NAMPT/Visfatin, TNFRSF1A, ETS1, SRC-1, FN1, APLP2, DMBT1/SAG, AIB1, AZIN1)." (PMID 23122428, 2012). "Indeed, knockdown of either UBE2F or SAG blocked full activation of mTORC1 stimulated by both amino acid and glucose (C and EV3B–G) in multiple cancer cell lines, implying that the UBE2F-SAG axis affects intrinsic activity of mTORC1." (PMID 39762645, 2025). "Hence, SAG-UPS was proposed to be an efficient target for developing therapeutics against autoimmune diseases and cancers." (PMID 26492374, 2015). "Upregulated SAG in HCC tissues correlates with imbalanced anti-/proapoptotic proteins, in which proapoptotic proteins are ubiquitinated, hence providing survival advantage to cancer cells." (PMID 27551463, 2015).
retinopathy (1 paper, 2021). "Dark-adapted red flash ERGs aid diagnosis of rod- and S-cone monochromacy, cone dystrophy, vitamin A deficiency, RDH5-retinopathy, SAG- or GRK1-retinopathy, some cases of rod-cone dystrophy, RGS9- and R9AP-retinopathy and colour vision deficiencies." (PMID 34045684, 2021).
SAG also shares sentences with these, for which no sentence is quoted: uveitis (9 papers); retinal degeneration (6); Autoimmunity (3); Behcet disease (2); pancreatic cancer (2); adenocarcinoma (1); adenoma (1); age (1); autoimmune retinopathy (1); autosomal recessive congenital stationary night blindness (1); brain injury (1); co-infection (1); Cognitive impairment (1); endothelial dysfunction (1); Hepatitis (1); keloid (1); lung disease (1); measles (1); mumps (1); neurodevelopmental disorder (1); non-alcoholic fatty liver disease (1); Obesity (1); ocular hypertension (1); ocular onchocerciasis (1); Oguchi disease type 2 (1); pancreatic (1); panuveitis (1); Photophobia (1); prostate (1); psoriasis (1).
A further 10 diseases each share a sentence with SAG in 1 paper.